APOB (apolipoprotein B)
Diseases named in the same sentence as APOB in open-access papers (continued):
Sharing a sentence is not in itself a finding about the gene and the disease.
septic shock (1 paper, 2024). Shock caused by infection; frequently caused by gram negative bacteria, although some cases have been caused by other bacteria, viruses, fungi, and protozoa; characterized by fever, chills, tachycardia, tachypnea, and hypotension. "Second, the distribution of apoB-depleted plasma’s anti-inflammatory capacity was sparser (reflecting more intragroup variation) for patients with more severe disease (i.e. septic shock, SOFA > 8, lactate > 18mg/dL)." (PMID 38603717, 2024).
Shock (1 paper, 2025). The state in which profound and widespread reduction of effective tissue perfusion leads first to reversible, and then if prolonged, to irreversible cellular injury. "Themodel identified critical predictors such as FFA, cardiogenic shock, HbA1c, ApoB,diuretic use, LVEF, BNP, BMI, Killip ≥II, and UA, highlighting themultifactorial complexity of MACEs risk." (PMID 40475716, 2025).
small bowel adenocarcinoma (1 paper, 2022). "Four target genes (APOA4, APOB, COL1A2, FN1) may be involved in the pathogenesis of small bowel adenocarcinoma." (PMID 36171259, 2022).
spina bifida (1 paper, 2020). A congenital neural tube defect in which vertebrae are not fully formed. "Variants in the lipid metabolism genes APOB and LEPR appear to contribute to lumbar sacral spina bifida in the present study." (PMID 32650820, 2020).
spina bifida aperta (1 paper, 2020). "In eleven cases affected by thoracic lumbar spina bifida aperta there were 3 PDRVs in the lipid metabolism genes LEPR and APOB (P = 0.029)." (PMID 32650820, 2020).
spinal muscular atrophy (1 paper, 2020). A motor neuron disease that affect the muscles, and characterized by muscle weakness and atrophy resulting from progressive degeneration and irreversible loss of the anterior horn cells in the spinal cord (i.e., lower motor neurons) and the brain stem nuclei. "Examples include the pursuit of modifying the splicing of apolipoprotein B (APOB) pre-mRNA to lower circulating cholesterol levels and of survival of motor neuron 2 (SMN2) pre-mRNA for treatment of spinal muscular atrophy." (PMID 33253191, 2020).
sporadic amyotrophic lateral sclerosis (1 paper, 2022). Sporadic amyotrophic lateral sclerosis is a amyotrophic lateral sclerosis in which there is no known cause, such as no family history. "Targeted removal of apolipoprotein B-100 from sporadic amyotrophic lateral sclerosis CSF via filtration or immunodepletion successfully attenuated the neurotoxic capacity of sporadic amyotrophic lateral sclerosis CSF to induce motor disability, motor neuron death, and TDP-43 translocation." (PMID 36043141, 2022).
staphylococcal infection (1 paper, 2021). An infection caused by Staphylococcus. "Moreover, mice lacking plasma apoB are more susceptible to invasive staphylococcal infections, highlighting that apoB is an important innate defense effector against S. aureus." (PMID 34321507, 2021).
Stickler syndrome (1 paper, 2023). Stickler syndrome is an inherited vitreoretinopathy characterized by the association of ocular signs with more or less complete forms of Pierre-Robin sequence, bone disorders, and sensorineural deafness (10% of cases). "Since some of FHBL and Stickler syndrome symptoms overlap, we cannot solely attribute all the characteristics observed in our proband to the variant discovered in the APOB gene." (PMID 37384046, 2023).
stomach tumors (1 paper, 2023). "Apolipoprotein B mRNA editing enzyme, Catalytic polypeptide-like (APOBEC) signature co-occurred with HRd and was mutually exclusive with MMRd in stomach tumors." (PMID 37393385, 2023).
thalassemia (1 paper, 2021). An inherited blood disorder characterized by a decreased synthesis of one of the polypeptide chains that form hemoglobin. "Moreover, 3 female patients had an APOB variant and one was found to be a carrier of a thalassemia-related variant." (PMID 33401665, 2021).
Thrombocytopenia (1 paper, 2024). A reduction in the number of circulating thrombocytes. "Platelet counts decreased significantly with both LPS and InvLNPs encapsulating the native ApoB sequence (siApoB Nat) indicating acute thrombocytopenia (decreased platelet counts)." (PMID 39274180, 2024).
thyrotoxicosis (1 paper, 2024). A hypermetabolic syndrome caused by the elevation of thyroid hormone levels in the serum. "An intronic variant, rs12720793, in APOB gene is also associated with thyrotoxicosis in the FinnGen Biobank (P < 0.008)." (PMID 39261665, 2024).
tongue cancer (1 paper, 2026). A malignant neoplasm affecting the tongue. "Importantly, we identified a tongue cancer-enriched NIRF OCSCC subgroup exhibiting significantly increased endogenous clock-like mutagenesis, while another NIRF subgroup manifested with elevated apolipoprotein B mRNA editing enzyme catalytic polypeptide-like (APOBEC)-associated mutagenesis." (PMID 42031720, 2026).
Turner syndrome (1 paper, 2017). Turner syndrome is a chromosomal disorder associated with the complete or partial absence of an X chromosome. "Eight TFs and four ERFs are among the differentially expressed genes, as well as eight genes associated with Turner syndrome (PROCR, NR3C1, INSR, APOB, BMP15, F8, IL6, and WAS) and two genes that are haploinsufficient in humans (RAD50 and SLC33A1)." (PMID 28818098, 2017).
ulcerative colitis (1 paper, 2022). An inflammatory bowel disease involving the mucosal surface of the large intestine and rectum. "The mutation of the APOB gene in CRC associated with ulcerative colitis was found by whole exon sequencing, and there was a significant difference between ulcerative colitis-associated CRC and scattered CRC." (PMID 35733095, 2022).
uterine cancer (1 paper, 2025). Primary or metastatic malignant neoplasm involving the uterine corpus and/or the cervix. "In the context of CTRP6 mutations, the significantly reduced expression of APOB may be linked to the development of uterine cancer." (PMID 39979869, 2025). "The downregulation of APOB could potentially disrupt lipid metabolism and transport, contributing to the metabolic alterations often observed in cancer cells and promoting tumor progression in uterine cancer." (PMID 39979869, 2025).
cardiovascular disease (299 papers, 2006 to 2026). "Our study adds by showing sex differences in some traits related to psychological disorders as well as ApoB and showing stronger associations in men than women for common cardiovascular diseases." (PMID 40498079, 2025). "Recent studies have shown that ApoA1 and ApoB are more accurate predictors of cardiovascular disease risk." (PMID 39931360, 2025). "Associations of LDL-cholesterol with all-cause, cardiovascular disease mortality stratified by the ApoB median." (PMID 40642933, 2025). "Despite the low prevalence of altered LDL-c and ApoB values, these lipid parameters are of great relevance in clinical practice due to their great impact as a risk factor for cardiovascular diseases." (PMID 38534969, 2024). "The smooth curve fitting diagram revealed differences in the relationship between TT concentration and apoB among individuals with different cardiovascular disease (CVD) risk factors." (PMID 38435750, 2024). "Specifically, apoB promotes the accumulation of cholesterol in the atheromatous plaque and its plasma value is related to the risk of cardiovascular disease." (PMID 39337423, 2024). "Ox-PL/apoB levels were associated with cardiovascular disease extent identified by coronary angiography, and with the extent and 5-year progression of carotid and femoral atherosclerosis independently of other cardiovascular risk factors except Lp(a)." (PMID 38255810, 2024). "In recent years, several investigations have shed light on the significance of apoA-I, apoB, and the apoB/apoA-I ratio in predicting and assessing susceptibility to cardiovascular diseases." (PMID 38978811, 2024). "Apolipoprotein is a constituent of lipoproteins, and its ratio levels (ApoB/ApoA1 ratio) are considered an independent risk factor for cardiovascular diseases." (PMID 39081429, 2024). "Elevated ApoB levels, indicative of a high concentration of atherogenic lipoprotein particles, are strongly associated with an increased risk in cardiovascular diseases." (PMID 39062066, 2024). "Patients with T2DM have higher levels of small dense LDL (ApoB) compared with healthy individuals, which increases the risk of cardiovascular disease (CVD) in T2DM." (PMID 36788517, 2023). "Image quantitative analysis of different fat depots combined with circulating ApoB data will provide a more accurate cardiovascular disease risk prediction program." (PMID 37047284, 2023). "The association of ApoB with specific fat depot features remains to be explored to better co-predict cardiovascular disease risk." (PMID 37047284, 2023). "It has been found that aging‐related processes can substantially impact the role of lipid‐related genes (including ApoB and ApoE allele) in regulation of TC and onset of cardiovascular disease." (PMID 34913545, 2022). "When the level of apoB increases, individuals have an increased risk of cardiovascular disease, while reducing the level of apoB can reduce cardiovascular disease." (PMID 35657779, 2022). "The ratio of ApoB/ApoA-I has been recognized as a marker for cardiovascular disease, the lower ApoB/ApoA-I ratio is associated with lower risk of cardiovascular diseases." (PMID 36010480, 2022). "For example, a study in Chinese diabetic patients showed that the ApoB/ApoA1 ratio predicted cardiovascular disease risk in men." (PMID 36016824, 2022). "Our positive control exposure analyses confirmed that higher circulating LDL-cholesterol and apolipoprotein B were related to higher risk of several cardiovascular disease outcomes." (PMID 35692035, 2022). "The INTERHEART study had proved that lower apoB/non–HDL-C was correlated with lower risk of cardiovascular disease, which is consistent with our result." (PMID 35937834, 2022). "The association between apolipoprotein B and cardiovascular disease has been well established in epidemiological studies." (PMID 33639994, 2021).
cardiovascular disease (continued). "High levels of Lp(a) and ApoB and low levels of ApoA-Ι are risk factors for cardiovascular disease as well as kidney disease." (PMID 34627286, 2021). "The ratio of apolipoprotein B100 to apolipoprotein A1 (ApoB100/ApoA1), a strong independent risk factor for cardiovascular diseases, was significantly increased." (PMID 34938772, 2021). "ApoA1 concentrations are inversely and ApoB levels are positively correlated with the risk of cardiovascular diseases." (PMID 34444289, 2021). "High serum Lipoprotein(a) (Lp(a)) level and Apolipoprotein B/Apolipoprotein AΙ (ApoB/ApoA-Ι) ratio are risk factors for cardiovascular disease and kidney disease and have been found to be correlated with the prevalence and prognosis of various kidney diseases." (PMID 34627286, 2021). "So far, variants on APOB were mainly investigated for associations with cardiovascular disease showing a different effect based on population ethnicity." (PMID 32443539, 2020). "The rs1609798 variant has been associated with apolipoprotein B concentrations, a marker of cardiovascular disease." (PMID 30781516, 2019). "For example, serum ApoB levels directly reflect the concentration of ApoB-LP particles and show a stronger correlation with cardiovascular disease risk than lipid metrics." (PMID 31366908, 2019). "Fasting Apolipoprotein B48 (ApoB48) is reported to be a well surrogate marker for postprandial lipidemia and have been repeatedly associated with cardiovascular disease." (PMID 30842592, 2019). "The size distribution of lipoprotein particles is also relevant to cardiovascular disease risk, as there are numerous classes of ApoB-LPs that can be differentiated by size and show varying degrees of atherogenicity." (PMID 31366908, 2019). "Lipoproteins containing apolipoprotein B modify associations of elevated urinary albumin excretion (UAE) with cardiovascular disease (CVD)." (PMID 30813431, 2019). "Ratios associated with increased cardiovascular disease risk were also negatively correlated with the HCV RNA:apoB/apoA-1 ratio (r = − 0.490; p = 0.015), TG/HDL-C ratio (r = − 0.450; p = 0.031) and total cholesterol/HDL-C ratio (r = − 0.450; p = 0.027)." (PMID 29423541, 2018). "The APOB gene encodes the apolipoprotein B (apoB) protein, which is an important component of many lipoproteins that are involved in cardiovascular disease." (PMID 30591010, 2018). "For example, the ApoB/apoA-1 ratio has been proposed as a simple, accurate risk factor for cardiovascular disease —the lower the apoB/apoA-I ratio, the lower is the risk." (PMID 29423541, 2018). "Although most therapies to reduce cardiovascular disease risk currently focus on reduction of LDLc and triglycerides, atherogenic proteins such as ApoB have also been suggested to have great predictive value." (PMID 29695967, 2018). "Because ApoB is a component of the lipid transport system linked to cardiovascular disease risk, this suggested a potential link between mtDNA integrity and physiological lipid regulation." (PMID 29157198, 2017). "Apolipoprotein A‐I (ApoA‐I) and apolipoprotein B‐100 (ApoB‐100) are amphipathic proteins that are strong predictors of cardiovascular disease risk." (PMID 28296203, 2017). "The percentage of subjects with the apoB/apoA-I ratio exceeding 0.9 (the accepted risk value of cardiovascular disease) was 19.1%." (PMID 25852220, 2015). "The epidemiological studies have revealed that a higher apoB/apoA-I ratio indicates a higher cardiovascular risk, such that the cut-off value of 0.9 has been proposed to define a risk of developing cardiovascular disease." (PMID 25852220, 2015). "High values of atherogenic indexes (TC/HDL-C, LDL-C/HDL-C and apoB/apoA-I) have been reported to be risk factors for cardiovascular disease that led to insulin resistant." (PMID 24558984, 2014).
cardiovascular disease (continued). "In the Apolipoprotein-related Mortality Risk Study (AMORIS), apoB was found to be a stronger marker of cardiovascular disease risk than LDL-C at any LDL-C levels, but especially in those having normal/low LDL-C levels." (PMID 23359805, 2013). "The ratio between apolipoprotein B and apolipoprotein A-I (apoB/apoA-I) has been suggested to be a powerful and more accurate predictor of future cardiovascular disease risk than total cholesterol and HDL cholesterol." (PMID 22848405, 2012). "To date, novel truncating mutations within APOB are continually being identified in FBHL patients devoid of cardiovascular diseases." (PMID 20423497, 2010). "Individuals with FHBL have reduced risk of cardiovascular diseases presumably owing to low plasma apoB and cholesterol concentrations." (PMID 20423497, 2010). "Apolipoprotein B (ApoB) plays a crucial role in assessing cardiovascular disease (CVD) risk." (PMID 40708721, 2025). "Moreover, sex-associated levels of atherogenic metabolites such as the apolipoprotein B to A1 ratio (ApoB:ApoA1) are proposed to contribute to the sex-associated risk of cardiovascular disease." (PMID 38609170, 2024). "Additionally, apolipoprotein B, which is associated with cardiovascular disease risk, was significantly reduced in the curcumin-treated group at the 6-, 9-, and 12-month visits." (PMID 39125322, 2024). "The authors suggested that an elevated ApoB/ApoA1 ratio may be independently related to cardiovascular disease and all-cause mortality." (PMID 38393015, 2024). "Also, the apolipoprotein B/apolipoprotein AI (ApoB/AI) ratio has emerged as a valuable predictor for cardiovascular disease risk and is associated with MASLD prevalence." (PMID 38397999, 2024). "A higher ratio of apoB to apoA1 is a recognized risk factor for cardiovascular disease." (PMID 36542145, 2023). "Lipoprotein(a) [Lp(a)], a low-density lipoprotein-like particle consisting of apolipoprotein A (ApoA) bounding covalently to apolipoprotein B (ApoB)-100, has been well considered as a critical risk factor of cardiovascular disease due to its atherogenic effects." (PMID 38288472, 2023). "Moreover, apolipoprotein B (ApoB) is considered a more accurate cardiovascular disease risk marker than low-density lipoprotein cholesterol (LDL-C) alone." (PMID 37869524, 2023). "At the same time, the association between ApoB and waist circumference and gynoid percent fat were both over-fitted in men, suggesting that the joint analyses of ApoB with waist circumference and gynoid percent fat are more suitable for women to predict the risk of cardiovascular disease." (PMID 37047284, 2023). "Another clinical study demonstrated that consumption of raw tomato (200 g/day) could prevent type 2 diabetes‐associated cardiovascular diseases by lowering systolic and diastolic blood pressure, upregulating ApoA1, and downregulating ApoB levels." (PMID 37823149, 2023). "Apolipoprotein B was identified to be associated with cardiovascular disease (CVD) progression." (PMID 37047284, 2023). "In addition, the average Apolipoprotein B/Apolipoprotein A-I ratio is greater than the value considered ideal for individuals at increased risk of cardiovascular disease." (PMID 37873769, 2023). "The main findings in this study were that, compared to egg whites, two eggs per day, alone or in combination with Annatto, resulted in similar concentrations of plasma LDL cholesterol, triglycerides, and apolipoprotein B, important biomarkers for cardiovascular disease risk." (PMID 36678239, 2023). "Overall, this study found that combined analysis of depot-specific DXA indicators such as arms percent fat, legs percent fat, trunk percent fat, total percent fat, android percent fat, gynoid percent fat and ApoB would indicate the risk of cardiovascular disease earlier than lipid biomarkers alone." (PMID 37047284, 2023).